TFE3 (transcription factor binding to IGHM enhancer 3)
Diseases named in the same sentence as TFE3 in open-access papers (continued):
Sharing a sentence is not in itself a finding about the gene and the disease.
renal cell carcinoma (continued). "TFE3 positivity is also observed; however, renal cell carcinomas with the ASPSCR1::TFE3 fusion also express CK and EMA epithelial markers and are positive for CD10 and RCC." (PMID 38291475, 2024). "This problem has been partially addressed among TFE3-rearranged renal cell carcinomas using an unsupervised transcriptomic analysis, which identified and characterized five molecular subtypes." (PMID 39410016, 2024). "TFE3 immunohistochemistry (TFE3‐IHC) is controversial in the diagnosis of TFE3‐rearranged renal cell carcinoma (TFE3‐rearranged RCC)." (PMID 38477529, 2024). "The morphology of renal cell carcinoma cells with the ASPSCR1::TFE3 fusion is often similar to that of ASPS cells." (PMID 38291475, 2024). "To thoroughly investigate the role of ARID2 in TFE3-rearranged renal cell carcinoma (TFE3-RCC) cells, we designed a series of in vitro and in vivo experiments." (PMID 39727945, 2024). "Understanding the unique traits of a rare kidney cancer type, TFE3-rearranged renal cell carcinoma, is important due to its poor response to usual treatments." (PMID 39085357, 2024). "In conclusion, TFE3-rearranged renal cell carcinoma is the most common renal cell carcinoma in children." (PMID 39502747, 2024). "We have described the case and performed a literature review to report the progress of current research on the treatment and prognosis of pregnant patients with Xp11.2/TFE3 translocation renal cell carcinoma." (PMID 38988705, 2024). "We have also described the main features of renal neoplasms carrying these translocations, known as TFE3-rearranged renal cell carcinoma and renal TFE3-rearranged PEComas." (PMID 39410016, 2024). "We describe the third case of TFE3-rearranged renal cell carcinoma with osseous metaplasia in a healthy 13-year-old male, presenting with worsening abdominal pain and hematuria." (PMID 39502747, 2024). "Their unsupervised clustering analysis suggested that melanotic Xp11 neoplasms and alveolar soft part sarcomas form a distinct cluster, clearly different from TSC-related PEComas and TFE3-rearranged renal cell carcinoma." (PMID 39410016, 2024). "Research indicates that patients with TFE3-positive renal cell carcinoma (RCC) are more prone to lymph node and distant metastases, exhibit higher tumor nuclear grades and clinical stages, and demonstrate shorter progression-free survival." (PMID 39440241, 2024). "TFE3-rearranged Renal Cell Carcinoma (TFE3-RCC) is an aggressive subtype of RCC characterized by Xp11.2 rearrangement, leading to TFE3 fusion proteins with oncogenic potential." (PMID 39727945, 2024). "Since its recognition by WHO in 2004, the diagnosis of TFE3-rearranged renal cell carcinoma (RCC) relied on microscopic appearance and TFE3 IHC." (PMID 39470841, 2024). "Xp11 tRCC is a distinct subtype of renal cell carcinoma characterized by the presence of multiple chromosomal translocations involving TFE3 on the Xp11.2 chromosome, resulting in sustained overexpression of TFE3." (PMID 36906611, 2023). "When facing TFE3-rearranged renal cell carcinoma, immunohistochemistry (IHC) is the most commonly used examination for diagnosis." (PMID 37367052, 2023). "The tumor cells were diffusely positive for HMB45, Melan-A, CK20, vimentin antibodies, and TFE3, suggesting that the tumor originated from perivascular epithelioid cells, excluding renal cell carcinoma." (PMID 37675231, 2023). "The main tumors related to TFE3 gene fusion include renal cell carcinoma, alveolar soft-part sarcoma (ASPS), epithelioid hemangioendothelioma, rare ossifying fibromyxoid tumors, malignant chondroid syringoma, and perivascular epithelioid cell tumors." (PMID 37528481, 2023). "Translocation renal cell carcinomas (T-RCCs) are driven by somatic translocation involving a member of microphtalmia (MiT) transcription factor family genes on chromosome X (i.e., TFE3, TFEB or MITF) with other partner genes." (PMID 36902045, 2023).
renal cell carcinoma (continued). "The TFE3/TFEB rearrangement renal cell carcinoma is characterized by translocations involving the TFE3 and TFEB genes." (PMID 37367052, 2023). "Translocation and transcription factor E3 (TFE3)-rearranged renal cell carcinoma (RCC) is a rare subtype of RCCs characterised by the fusion of the TFE3 transcription factor genes on chromosome Xp11.2 with one of the multiple genes." (PMID 37789903, 2023). "TFE3-rearranged renal cell carcinoma (RCC) is a rare subtype of renal tumor that primarily affects young women and is characterized by early metastasis and a poor prognosis." (PMID 37936602, 2023). "Positive expression was found in 23 of 25 (92%), 19 of 25 (76%), and 18 of 25 (72%) TFE3-rearranged renal cell carcinomas, using the same thresholds." (PMID 35980471, 2022). "As previously pointed out, TFE3-rearranged renal cell carcinoma is likely to be misdiagnosed as clear cell renal cell carcinoma if a restricted immunohistochemical panel is applied." (PMID 35980471, 2022). "TFE3/TFEB-rearranged renal cell carcinomas are characterized by translocations involving TFE3 and TFEB genes." (PMID 35980471, 2022). "Genomic studies identifying the genes for kidney cancer, including the VHL, PBRM1, MET, FLCN, fumarate hydratase, succinate dehydrogenase, TSC1, TSC2, and TFE3 genes are known to play role in renal cell carcinoma development." (PMID 35709632, 2022). "TFE3-rearranged renal cell carcinoma (RCC) is a rare but well characterised histological subtype of RCC with an aggressive clinical course and propensity for late metastases." (PMID 35530544, 2022). "The expression of Melan-A and HMB45 was significantly lower in TFE3-rearranged renal cell carcinoma compared with TFEB-rearranged renal cell carcinoma, even when a 5% cutoff was used (17% and 27% respectively)." (PMID 35980471, 2022). "Parvalbumin and CK7/S100A1 respectively are of paramount importance when TFE3/TFEB-rearranged renal cell carcinoma resembles oncocytoma and chromophobe renal cell carcinoma." (PMID 35980471, 2022). "A panel of immunohistochemistry markers useful to distinguish TFE3/TFEB-rearranged renal cell carcinoma from other common renal cell neoplasms should include cathepsin K, CA9, CK7, and parvalbumin." (PMID 35980471, 2022). "TFE3 gene fusions with variable gene partners occur in many neoplasms including renal cell carcinoma and lead to immunohistochemical (IHC) nuclear staining." (PMID 35225876, 2022). "Even a patchy expression should be considered a positive result, especially for TFE3-rearranged renal cell carcinoma in which melanogenesis markers are less consistent." (PMID 35980471, 2022). "AMACR is not useful in the differential diagnosis between papillary renal cell carcinoma and TFE3-rearranged renal cell carcinoma since both tumors are usually labeled for this marker, but it helps distinguish from TFEB-rearranged renal cell carcinoma." (PMID 35980471, 2022). "While 5 of 22 TFE3-rearranged renal cell carcinomas showed positivity for such marker in more than 20% of the cells (22%), the remaining 17 cases were completely negative or patchy positive for it." (PMID 35980471, 2022). "ASPSCR1 and Transcription factor E3 (TFE3) fusion is observed in tumors including alveolar soft part sarcoma (ASPS) and Xp11-associated renal cell carcinoma." (PMID 36291758, 2022). "Cathepsin K and parvalbumin are the two useful markers in the differential diagnosis between oncocytoma and TFE3/TFEB-rearranged renal cell carcinoma." (PMID 35980471, 2022). "On the other hand, no relevant statistical correlation was found with immunohistochemical expression of either CD10, AMACR, or CD13, in contrast with the data observed with TFE3-rearranged renal cell carcinomas." (PMID 35980471, 2022).
renal cell carcinoma (continued). "CD10 is not useful in the differential diagnosis between clear cell renal cell carcinoma and TFE3-rearranged renal cell carcinoma since both tumors are usually labeled for this marker, but it helps distinguish from TFEB-rearranged renal cell carcinoma." (PMID 35980471, 2022). "TFE3-rearranged renal cell carcinoma, as the name indicates, harbors TFE3 gene translocation which fuses with one of several other genes, such as ASPL (ASPSCR1), PRCC, SFPQ, CLTC, PARP14, RBM10, NONO, and MED15." (PMID 35980471, 2022). "This study aimed to investigate the expression profile of TFE3 in renal cell carcinoma (RCC) and the clinicopathological features as well as prognosis of TFE3-positive RCC." (PMID 36276115, 2022). "Xp11.2 translocation renal cell carcinoma (Xp11.2 tRCC), also known as transcription factor binding to IGHM enhancer 3 (TFE3)-fusion associated RCC, is recently stratified in the MiT (microphthalmia transcription factor) family tRCC as a new subset of RCC in the 2016 WHO classification." (PMID 33741027, 2021). "Furthermore, in renal cell carcinoma (RCC), increased TFE3 expression was associated with poor progression-free survival (PFS)." (PMID 34660181, 2021). "Conversely to TFE3-rearranged renal cell carcinoma, pure epithelioid PEComa/epithelioid angiomyolipoma constantly express cathepsin K, regardless of the type of translocation." (PMID 34069976, 2021). "TFE3-rearranged renal cell carcinomas display heterogeneous morphological features simulating most of the subtypes of renal cell carcinoma." (PMID 34069976, 2021). "Translocation renal cell carcinomas comprise two different tumors molecularly characterized by specific gene translocations, namely TFE3-rearranged renal cell carcinoma, the most common subtype, and TFEB-rearranged renal cell carcinoma." (PMID 34069976, 2021). "Xp11.2 translocation carcinoma is a distinct subtype of renal cell carcinoma characterized by translocations involving the TFE3 gene." (PMID 31955345, 2020). "TFE3 Xp11.2 translocation renal cell carcinoma (TFE3-RCC) generally progresses more aggressively compared with other RCC subtypes, but it is challenging to diagnose TFE3-RCC by traditional visual inspection of pathological images." (PMID 32286325, 2020). "Dual mTORC1/2 inhibition suppresses Akt/mTOR signaling more effectively than selective mTORC1 inhibition and demonstrates in vivo preclinical efficacy against TFE3-fusion renal cell carcinoma." (PMID 31519159, 2019). "Xp11 translocation renal cell carcinoma is a distinctive subtype of renal cell carcinoma, characterized by several chromosomal translocations involving the TFE3 gene, located on chromosome Xp11.2." (PMID 31382581, 2019). "Renal cell carcinomas (RCC) harboring a TFE3 gene fusion (TfRCC) represent an aggressive subset of kidney tumors." (PMID 31519159, 2019). "The aim of our study was to explore the prognostic values of these ratios in patients with Xp11.2 translocation/TFE3 gene fusions renal cell carcinoma (Xp11.2 tRCC)." (PMID 29890986, 2018). "Xp11.2 translocation/TFE3 gene fusions renal cell carcinoma (Xp11.2 tRCC) was first listed as a new type of renal cell carcinoma (RCC) in the 2004 by the World Health Organization (WHO)." (PMID 29890986, 2018). "The data of clinicopathologic features, TFE3 and cathepsin K IHC, PRCC-TFE3 FISH assay of PRCC-TFE3 renal cell carcinomas." (PMID 28949976, 2017). "Xp11 translocation renal cell carcinoma (RCC) is characterized by chromosome translocations involving the TFE3 gene at the Xp11 breakpoint." (PMID 28415646, 2017). "TFE-RCCs are a group of renal cell carcinomas caused by chromosomal translocations involving TFEB and TFE3 genes and representing around 2% of all RCCs, and almost 12% of papillary type II RCCs." (PMID 27668431, 2016). "Xp11.2 translocation/transcription factor E3 (TFE3) rearrangement renal cell carcinoma (RCC) is a rare subtype of RCC with limited clinical and pathological data." (PMID 27733182, 2016).
renal cell carcinoma (continued). "TFE-fusion renal cell carcinomas (TFE-fusion RCCs) are caused by chromosomal translocations that lead to overexpression of the TFEB and TFE3 genes." (PMID 27668431, 2016). "Xp11.2 or TFE3 translocation renal cell carcinoma (RCC) is one of the new entities added in the 2004 World Health Organization (WHO) classification of renal tumors." (PMID 26415891, 2015). "We report the first two documented cases of Xp11.2 translocation/TFE3 fusion renal cell carcinomas in Slovenia in young adult males with a long and unusual history." (PMID 24991210, 2014). "Gene fusions involving clathrin heavy chain (CLTC) have been described in various leukemias (CLTC/ALK) and in renal cell carcinoma (CLTC/TFE3)." (PMID 23637631, 2013). "This drug was tested in a Phase II study (NCI Clinical Trial NCT00557609) examining the drug's effect on Microphthalmia Transcription Factor Family (MiT) tumors, which include ASPS, clear cell carcinoma, and renal cell carcinomas bearing a TFE3 translocation." (PMID 22566752, 2012). "Translocations of the genes encoding the related transcription factors TFE3 and TFEB are almost exclusively associated with a rare juvenile subset of renal cell carcinoma and lead to over-expression of TFE3 or TFEB protein sequences." (PMID 17705868, 2007). "Renal cell carcinoma with Xp11.2 translocation with TFE3 gene fusion is a rare subtype of renal carcinoma that occurs more frequently in the pediatric population (20–25% of kidney cancer cases in children compared to 1–4% in adults), with a worse prognosis in adult patients compared to children." (PMID 39851801, 2025). "However, TFE3 gene breaks down at Xp11.2, and equilibrium translocations with ASPL, PSF, and other genes form new fusion genes, contributing to TFE3 or TFEB fusion gene formation and their high expression in vivo, thus causing renal cell carcinoma." (PMID 38261736, 2024). "Nevertheless, since the morphology of TFE3-rearranged renal cell carcinoma is variable and the immunophenotype is not always diagnostic, the diagnosis often necessitates the demonstration of the TFE3 gene rearrangement." (PMID 39410016, 2024). "ARID2 plays a crucial tumor-suppressive role in TFE3-rearranged Renal Cell Carcinoma (TFE3-RCC)." (PMID 39727945, 2024). "In this view, it is indeed worth mentioning that SFPQ/PFS::TFE3-rearranged renal cell carcinoma may morphologically mimic TFEB-rearranged renal cell carcinoma." (PMID 39410016, 2024). "The diagnosis rendered was TFE3-rearranged renal cell carcinoma with osseous metaplasia." (PMID 39502747, 2024). "Spatial transcriptomic analysis could also uncover valuable data, such as gene expression signatures in tumors like TFE3-rearranged renal cell carcinoma and PEComa, which exhibit tumor heterogeneity." (PMID 39410016, 2024). "Among the commonly used immunohistochemical markers, CA9 and cytokeratin 7 are the most helpful immunostainings for differentiating TFE3-rearranged renal cell carcinoma from common renal cell tumors as they are frequently negative in TFE3-rearranged renal cell carcinoma." (PMID 39410016, 2024). "The several TFE3 fusion partners may also explain the different morphologies seen in TFE3-rearranged renal cell carcinomas." (PMID 39410016, 2024). "A final immunomorphologic diagnosis of TFE3-rearranged renal cell carcinoma was rendered." (PMID 39206137, 2024). "When comparing the biological behavior of tumors classified as TFE3-rearranged renal cell carcinoma with neoplasms diagnosed as TFE3-rearranged PEComa, both show aggressiveness and young age at the time of identification, with the former appearing more aggressive and arising in younger patients." (PMID 39410016, 2024). "The function of the chimeric TFE3 fusion proteins may also vary, potentially explaining the diverse histologic features observed in this type of renal cell carcinoma." (PMID 39410016, 2024).
renal cell carcinoma (continued). "However, the translocation is balanced in TFE3-rearranged renal cell carcinoma and unbalanced in alveolar soft part sarcoma, likely accounting for their clinical and morphological differences." (PMID 39410016, 2024). "In addition to histomorphology, the immunophenotype of renal epithelioid-AML overlaps with MiT family renal cell carcinoma with TFE3 or TFEB translocation." (PMID 36740682, 2023). "Therefore, attention should be paid and the impact of the genes that are fused with should be determined as much as possible both in the diagnosis and in the treatment of TFE3-rearranged renal cell carcinoma." (PMID 37367052, 2023). "In conclusion, since TFE3/TFEB-rearranged renal cell carcinoma may mimic several histotypes, an immunohistochemical panel to differentiate them from common renal cell tumors should include cathepsin K, CA9, CK7, and parvalbumin." (PMID 35980471, 2022). "TFEB or TFE3 fusion with other partner genes may be the initiating factors for MITF translocation renal cell carcinoma." (PMID 36550835, 2022). "Expression of CK7 and parvalbumin along with the absence of S100A1 is characteristic of chromophobe renal cell carcinoma, whereas strong and diffuse labeling of S100A1 along with the under-expression of CK7 and parvalbumin are typical of TFE3/TFEB-rearranged renal cell carcinoma." (PMID 35980471, 2022). "The authors suggested that the MCS is genetically related to tumors with TFE3 rearrangements such as renal cell carcinoma and might have genetic heterogeneity." (PMID 35225876, 2022). "Moreover, in TFEB-rearranged renal cell carcinoma, cathepsin K and melanogenesis markers are constantly positive, whereas TFE3-rearranged renal cell carcinoma stains for cathepsin K in roughly half of the cases, HMB45 in 8% and Melan-A in 22%." (PMID 35980471, 2022). "TFE3-rearranged renal cell carcinomas revealed the same results." (PMID 35980471, 2022). "In addition, color feature is regard as an important feature for the diagnosis of TFE3 Xp11.2 translocation renal cell carcinoma via WSI." (PMID 35936712, 2022). "Moreover, previous manuscripts mainly focused on the differential diagnosis between TFE3-rearranged renal cell carcinoma and clear cell renal cell carcinoma." (PMID 35980471, 2022). "About TFE3-rearranged renal cell carcinomas, immunolabeling was observed in roughly half of the cases (54% and 50% using the threshold of 5% and 10% or 20% positive cells respectively) whereas all the eleven TFEB-rearranged renal cell carcinomas evaluated stained positive for cathepsin K." (PMID 35980471, 2022). "Similar results were observed when TFE3-rearranged renal cell carcinoma was considered." (PMID 35980471, 2022). "However, as TFE3-rearranged renal cell carcinoma, other gene fusion partners have been recently detected (COL21A1, CADM2, KHDRBS2, ACTB, EWSR1, CTLC, and NEAT1), as well as tumors harboring TFEB gene amplification despite translocation." (PMID 35980471, 2022). "TFE3-rearranged renal cell carcinoma may show a solid, trabecular, or microcystic pattern, mimicking clear cell renal cell carcinoma, papillary renal cell carcinoma, and clear cell papillary renal cell tumor." (PMID 35980471, 2022). "Furthermore, S100A1 was typically positive and CK7 was usually negative regardless of the cutoff used either considering the overall MiT family translocation renal cell carcinomas or TFE3 and TFEB-rearranged renal cell carcinoma separately." (PMID 35980471, 2022). "NONO-TFE3 translocation renal cell carcinoma (NONO-TFE3 tRCC) is one of the subtypes of Xp11.2 translocation/TFE3 fusion-associated renal cell carcinoma (Xp11.2 tRCC), which is also known as TFE3-fusion associated RCC as a new subset of RCC by WHO in 2016." (PMID 35897085, 2022). "Indeed, cathepsin K is a recognized diagnostic tool for the identification of TFE3/TFEB-rearranged renal cell carcinoma, TFEB-amplified renal cell carcinoma, and pure epithelioid PEComa/epithelioid angiomyolipoma." (PMID 34069976, 2021).